L1CAM (L1 cell adhesion molecule)
Description:
Neural cell adhesion molecule involved in the dynamics of cell adhesion and in the generation of transmembrane signals at tyrosine kinase receptors. During brain development, critical in multiple processes, including neuronal migration, axonal growth and fasciculation, and synaptogenesis. In the mature brain, plays a role in the dynamics of neuronal structure and function, including synaptic plasticity.
Synonyms: N-CAM-L1; NCAM-L1; CD171; CAML1; MIC5; HSAS; HSAS1; HYCX; MASA; N-CAML1; S10; SPG1
Tractability: Antibody: UniProt places it where antibodies can reach, with high confidence; its Gene Ontology location is reachable by antibodies, with high confidence; UniProt predicts a signal peptide or a membrane-spanning region. PROTAC: ubiquitination databases record sites on it; its protein half-life has been measured.
Target class: Adhesion
Gene: Protein-coding gene on chromosome X (153,861,511 to 153,886,204, reverse strand). Ensembl gene ENSG00000198910.
Subcellular location: Cell membrane; Cell projection, growth cone; Cell projection, axon; Cell projection, dendrite
Subcellular location (Human Protein Atlas): Nucleoplasm; Plasma membrane
Pathways (Reactome):
Developmental Biology: Interaction between L1 and Ankyrins; L1CAM interactions; Recycling pathway of L1; Signal transduction by L1
Hemostasis: Basigin interactions
Gene Ontology:
Molecular function: protein binding; protein domain specific binding; axon guidance receptor activity
Biological process: axon development; axon guidance; cell migration; cell-matrix adhesion; neuron projection development; synapse organization; cell adhesion; chemotaxis; homophilic cell-cell adhesion; nervous system development; positive regulation of axon extension
Cellular component: axon; cell surface; extracellular matrix; focal adhesion; neuronal cell body; plasma membrane; axonal growth cone; dendrite; growth cone
Gene-disease validity (ClinGen):
ClinGen rates the evidence that L1CAM causes each of these diseases.
L1 syndrome (X-linked): Definitive. L1 syndrome is a mild to severe congenital X-linked developmental disorder characterized by hydrocephalus of varying degrees of severity, intellectual deficit, spasticity of the legs, and adducted thumbs.
Homologues: Orthologues: chimpanzee L1CAM (99% identical), macaque L1CAM (97% identical), rabbit L1CAM (91% identical), pig L1CAM (91% identical), dog L1CAM (90% identical), mouse L1cam (89% identical), guinea pig L1CAM (87% identical), rat L1cam (83% identical), tropical clawed frog l1cam (48% identical), zebrafish l1cama (41% identical). Paralogues in human: NRCAM (38% identical), CHL1 (37% identical), NFASC (34% identical), CNTN2 (24% identical), CNTN3 (24% identical), CNTN4 (24% identical), CNTN5 (23% identical), CNTN6 (23% identical), CNTN1 (22% identical), ROBO2 (19% identical), NEO1 (18% identical), ROBO1 (18% identical), and 24 more.
Diseases named in the same sentence as L1CAM in open-access papers:
L1CAM is named in the same sentence as 297 diseases in open-access papers, as found by Europe PMC text mining. Sharing a sentence is not in itself a finding about the gene and the disease. The quoted sentences say what the papers report.
endometrial cancer (77 papers, 2010 to 2026). Primary or metastatic malignant neoplasm involving the endometrium (mucous membrane that lines the endometrial cavity). "Given the frequent reports of L1CAM association with endometrial cancer and more aggressive tumors, as well as the known susceptibility of L1CAM to protease activity, it is worth wondering if a soluble form of L1CAM exists." (PMID 40870967, 2025). "In another retrospective study of 312 endometrial carcinoma samples, almost 30% of the samples expressed L1CAM, and this expression was associated with distant metastasis but not with disease-free or overall survival." (PMID 40870967, 2025). "Other molecular parameters that are prognostic in endometrial cancer include overexpression of L1CAM and loss of oestrogen (ER) and/or progesterone receptors (PR), both of which are linked to a higher risk of recurrence and death." (PMID 35530346, 2022). "Here, the authors report their findings that overexpression of the transmembrane protein L1CAM predicts poor response to platinum‐based chemotherapy in high‐risk endometrial cancer patients." (PMID 35429348, 2022). "The use of this higher threshold is justified by previous observations in high‐risk endometrial cancer, in which L1CAM expression >50% proved to be more appropriate in discriminating patients with a higher rate of distant metastasis." (PMID 35429348, 2022). "L1CAM overexpression has been associated with poor outcome in endometrial carcinoma, as well as in several other tumors." (PMID 35892892, 2022). "In endometrial cancer, L1CAM expression is associated with myometrial invasion, cervical involvement, positive LVSI, positive lymph nodes and poor overall survival 21-23." (PMID 34659530, 2021). "In our cohort, L1CAM expression was associated with an increased likelihood of death from endometrial cancer." (PMID 34659530, 2021). "Dellinger found L1CAM expression was an independent predictor of poor survival in endometrial cancer and was associated with advanced stage, high-risk endometrial cancer." (PMID 32509846, 2020). "L1CAM has also been assessed as a biomarker for preoperative risk factor stratification of endometrial carcinoma." (PMID 32429448, 2020). "The association between L1CAM expression and higher grade has been shown by two recent reports including endometrial cancer of various histology and stages." (PMID 29980240, 2018). "In the era of personalized approach and innovative biotechnology, expression of L1CAM has been associated with aggressive subtypes of endometrial carcinoma." (PMID 29980240, 2018). "In this study, beyond the expression of L1CAM, we also analyze its association with classical risk factors in endometrial carcinomas of endometrioid type, according to the International Federation of Gynecology and Obstetrics (FIGO) stages I-III." (PMID 30557309, 2018). "L1 cell adhesion molecule (L1CAM) overexpression has been reported to be strongly associated with poor prognosis in early stage endometrial cancer (EC)." (PMID 27488577, 2016).
endometrial cancer (continued). "Expression of L1CAM has been reported to be associated with aggressive subtypes of endometrial cancer, including NEECs27." (PMID 27830726, 2016). "The association between L1CAM expression and higher grade has also been shown by two recent reports including endometrial cancer of various histologies and stages." (PMID 27488577, 2016). "Recently, expression of L1 cell adhesion molecule (L1CAM) has been associated with aggressive subtypes of endometrial carcinoma." (PMID 26891628, 2016). "The aim of this study was to determine if L1CAM expression, a recently reported biomarker for aggressive tumor behavior in endometrial carcinoma, was associated with clinicopathological features of EECs." (PMID 26891628, 2016). "L1 cell adhesion molecule (L1CAM) has been identified as a poor prognostic factor for human endometrial cancer; however, the molecular mechanisms underlying its role in tumor progression remain unclear." (PMID 41595121, 2026). "Several recent studies have shown that L1CAM expression is associated with high-risk endometrial cancer, retains its prognostic significance in multivariate analysis, and might predict response to chemotherapy." (PMID 40870967, 2025). "L1CAM is also recognized as a reliable marker for mature TLS associated with endometrial cancer." (PMID 39620224, 2024). "To conclude, we here demonstrate that presence of mature tertiary lymphoid structures, as assessed using L1CAM immunohistochemistry, improves prediction accuracy of recurrence and death beyond clinicopathological risk factors and molecular class in high-risk endometrial cancer patients." (PMID 35296668, 2022). "L1CAM is included as a risk variable in the ongoing PORTEC-4a trial to evaluate vaginal recurrence after adjuvant treatment or observation based on molecular-integrated risk profile in women with early-stage endometrial carcinoma." (PMID 35158919, 2022). "Furthermore, elevated L1CAM mRNA levels were highly associated with distant recurrence of endometrial cancer." (PMID 27233077, 2016). "In a bioinformatics analysis of endometrial cancers from the TCGA database, the regulators of RNA methylation and their relationship with prognosis and the immune microenvironment were studied, revealing that L1CAM acts as an RNA methylation-related gene and is implicated in the immune response." (PMID 40870967, 2025). "Furthermore, in absence of a specific molecular profile, the identification of L1CAM can be a useful predictor of early relapse in high risk endometrial cancer type, and, similarly, the use of machine learning algorithms, using multiple classical parameters, can help to build a prognostic model." (PMID 37835017, 2023). "Since the NSMP is the most heterogeneous subgroup, we believe that L1CAM may represent a relevant candidate biomarker to complement both prognostic stratification and prediction of chemotherapy benefit in patients with high-risk endometrial cancer." (PMID 36358847, 2022). "The aim of this study was to investigate whether L1CAM can predict lymph node metastasis and could therefore be used preoperatively to identify patients with low to high-intermediate risk endometrial cancer who would profit from a lymphadenectomy and an adjuvant treatment." (PMID 34659530, 2021). "In the retrospective analysis conducted by the European Network for Individualised Treatment of Endometrial Cancer Centres, the expression of L1CAM was found in 10% of the 935 stage I endometrioid ECs and was a strong predictor of poor outcome." (PMID 41561510, 2025). "Like Horeweg and co‐workers, we also observed L1CAM expression in FDCs in lymphoid follicles surrounding a POLE‐ultramuted endometrial cancer." (PMID 40289262, 2025).
endometrial cancer (continued). "In 183 patients with early-stage endometrial cancer, L1CAM expression (clone 14.10, dilution 1:50, 10% cutoff) showed approximately 10% positive cases, and L1CAM was an independent prognostic factor in multivariate analysis." (PMID 40870967, 2025). "In recent years, studies of several large cohorts of patients with endometrial cancer have revealed that L1CAM acts as a poor prognostic factor, in most cases independent of other parameters." (PMID 40870967, 2025). "In 2013, one of the first numerous studies on L1CAM expression in endometrial cancer appeared, corresponding to a retrospective multicenter cohort of 1021 endometrial cancer tissues from stage I endometrioid adenocarcinomas." (PMID 40870967, 2025). "Apart from immunohistochemistry, only a few other methods of studying L1CAM in endometrial cancer have been applied." (PMID 40870967, 2025). "Multiple studies have also shown that L1CAM immunohistochemical expression has prognostic significance for endometrial cancer." (PMID 40150014, 2025). "A study of 162 patients with endometrial cancer revealed L1CAM (tissue microarrays, monoclonal antibody, clone UJ127.11, dilution 1:10,000, 10% cutoff) as an independent prognostic factor." (PMID 40870967, 2025). "One of the largest series considering L1CAM expression used the 14.10 antibody (dilution 1:100) and the 10% cutoff value to examine 1199 endometrial carcinomas." (PMID 40870967, 2025). "With almost a decade of research on L1CAM and endometrial carcinoma, the results of its expression in thousands of patients have been published." (PMID 40870967, 2025). "In 65 patients with endometrial carcinoma, serum L1CAM levels were higher at diagnosis than during follow-up, but no statistically significant augmentation was found in patients upon disease recurrence." (PMID 40870967, 2025). "In the present study, L1CAM was utilized as a novel marker to stratify patients with endometrial cancer (EC) and was anticipated to serve as a predictive marker following adjuvant treatments, such as chemotherapy." (PMID 39734232, 2024). "Second, proteins such as MMR, L1CAM, and CTNNB1 have recently been reported to be associated with the prognosis of endometrial cancer, and the molecular classification of endometrial cancer proposed by TCGA has also gained wide attention." (PMID 39834947, 2024). "ARGs play important roles in the progression of several tumors, especially in the process of metastasis: FAIM2 overexpression is associated with adverse clinical outcome in lung cancer, L1CAM affects the prognosis of endometrial cancer (EC)." (PMID 37664042, 2023). "Further, CHRM2, GRIN1, L1CAM, and SEMA4F were found to be significantly associated with clinical stage, immune infiltration, immune response, and important signaling pathways in endometrial cancer." (PMID 36212450, 2022). "Further research is needed to confirm these observations, in order to establish the rationale for assessing the impact of L1CAM‐targeted strategies on endometrial cancer CSC subpopulation." (PMID 35429348, 2022). "Using L1CAM immunohistochemistry as a marker, TLS are found in 19% of high risk endometrial cancer patients and have a strong favorable prognostic impact of TLS, independent of clinicopathological and molecular factors." (PMID 35296668, 2022). "Here the authors identify L1CAM as a marker for mature TLS and show that the presence of TLS is associated with favorable prognosis in patients with endometrial cancer from the PORTEC-3 trial." (PMID 35296668, 2022). "We aimed to assess the association between L1CAM expression, the MELF pattern, and lymph node status in endometrial carcinoma." (PMID 35892892, 2022).
endometrial cancer (continued). "In endometrial carcinoma, both L1CAM overexpression and microcystic, elongated and fragmented (MELF) patterns of invasion have been related to epithelial-to-mesenchymal transition and metastatic spread." (PMID 35892892, 2022). "L1CAM (L1 cell adhesion molecule), which has already been described as predictive of worse outcomes in endometrial carcinoma, was upregulated in cluster A (N+ patients) with a fold change of 7.8." (PMID 35565317, 2022). "MiR‐146a and miR‐34a have been described as suppressors of L1CAM in gastric and endometrial carcinomas, while miR‐29a and miR‐21‐3p directly or indirectly upregulate L1CAM." (PMID 34228897, 2022). "Consecutive cases of endometrial carcinoma with MELF pattern were immunohistochemically assessed for L1CAM." (PMID 35892892, 2022). "As L1CAM has been associated with a more aggressive tumour biology and worse outcome, we investigated whether L1CAM can improve preoperative decision-making strategies and allows for avoidance of lymphadenectomy in a selected population of patients with endometrial cancer." (PMID 34659530, 2021). "The L1 cell adhesion molecule (L1CAM) is recognized as an important predictor and risk factor for recurrence and poor survival with both early-stage and advanced endometrial cancer." (PMID 34356280, 2021). "Among these, the tumor in which the prognostic role of L1CAM has been investigated most extensively is endometrial cancer." (PMID 32429448, 2020). "At the same time when TCGA classification was published, the L1 neuronal cell-adhesion molecule (L1CAM) gained attention as a specific prognosticator and potential therapeutic target in early-stage type I endometrial carcinoma." (PMID 32927671, 2020). "Multiple studies have shown the prognostic significance of L1CAM immunohistochemistry (IHC) in large cohorts of endometrial carcinoma." (PMID 32927671, 2020). "Among tumors of the gynecological tract, the role of L1CAM in cancer stemness has been studied in ovarian and endometrial carcinoma." (PMID 32429448, 2020). "In this work we have analyzed, by immunohistochemical and RT-qPCR analysis, the expression of L1CAM in a cohort of 113 endometrial cancers at different stages, which 50% have relapsed." (PMID 29980240, 2018). "The report by Dellinger and colleagues utilized TCGA data to show that L1CAM is an independent predictor of poor survival in endometrial cancer." (PMID 29666643, 2018). "L1CAM has been shown to be an important prognostic factor in endometrial carcinomas and is predictive of lymph node involvement." (PMID 30557309, 2018). "It is surprising in view of most previously cited data, but as it was already mentioned only 17% of stage I endometrioid endometrial cancers and up to 28% of all uterine cancers including type II and advanced stages tumors express L1CAM in their cells." (PMID 27832351, 2017). "In endometrial cancer, the expression of L1CAM has been shown to be a predictor of poor survival and this has been shown to be associated with an advanced stage." (PMID 29215599, 2017). "In recent studies, L1CAM has been identified as a possible marker of poor prognosis and relapse in patients with endometrial cancer both of type 1, type 2 and mixed morphology." (PMID 27832351, 2017). "In conclusion, we herein present a proof of concept to determine L1CAM status on the transcriptome level and to extend the number of reliable methods for L1CAM determinations in endometrial cancers." (PMID 27233077, 2016). "We were motivated to perform this investigation by means of a reliable and well-established quantitative technique as in various IHC studies a considerable range of different L1CAM positivity rates have been reported in endometrial cancer." (PMID 27233077, 2016). "In endometrial cancer, L1CAM staining has been described as diffuse and localized in tumor cells adjacent to the stroma, suggestive of the role of L1CAM in the migration and invasion of tumor cells." (PMID 27488577, 2016).